TNF (tumor necrosis factor)
Diseases named in the same sentence as TNF in open-access papers (continued):
Sharing a sentence is not in itself a finding about the gene and the disease.
autoimmune disease (continued). "Among these, we choose TNF-α, a multifunctional proinflammatory cytokine that belongs to the tumor necrosis factor superfamily and that may be a pathogenic factor in SS and other autoimmune diseases." (PMID 35432384, 2022). "Furthermore, the current results revealed that participants with higher adherence to the MDP show lower concentrations of IL-15, an immune cytokine implicated in autoimmune diseases that acts as a potent pro-inflammatory mediator inducing the expression of TNFα, IL-1 and INF-γ." (PMID 35624765, 2022). "Moreover, anti-tumor necrosis factor (TNF)-α therapy during autoimmune diseases may lead to the increased risk of NTM diseases as well as tuberculosis, suggesting that TNF-α is also crucial for host defense against NTM infection." (PMID 34552591, 2021). "In a conditional logistic regression model adjusted for disease duration, exposure to TNF inhibitors was associated with an increased risk of developing any inflammatory CNS events (adjusted OR, 3.01; 95% CI, 1.55-5.82; P = .001) in patients with all autoimmune diseases." (PMID 32421186, 2020). "Therefore, genetic variants of TNF-a may have aneffect on the susceptibility to autoimmune disease development and on its clinicalmanifestations." (PMID 30916218, 2019). "Vaccination with bacillus of Calmette-Guérin is currently being tested for treatment of various autoimmune diseases and this effect seems to be mediated by the expansion of regulatory T-cells and by selective death of auto reactive lymphocytes caused by activation of TNFα cascade." (PMID 31616649, 2019). "It is remarkable that both these patients had a family history of autoimmune diseases, a fact that could indicate an increased susceptibility of CNS demyelination, irrespectively of anti-TNF-α treatment and should be taken into consideration during the clinical evaluation of the patients." (PMID 28337644, 2017). "However, another possibility is the use of TNF antagonists which may have predisposed to development of secondary autoimmune disease." (PMID 25664229, 2015). "In autoimmune disease, where Th1/Th17-macrophage circuits dominate, steroid-sparing treatment targets TNF and IL-6 pathways." (PMID 41877771, 2026). "TNF α inhibitors such as adalimumab are widely used for autoimmune diseases, yet their long-term impact on tumor development in genetically susceptible individuals remains incompletely defined." (PMID 42130630, 2026). "This strategy represents a potential low-cost alternative to current TNF-blocking biologics for the treatment of autoimmune diseases." (PMID 42039199, 2026). "Considering the coexistence of these autoimmune diseases and the patient's previous exposure to anti-tumor necrosis factor therapy, treatment with the interleukin-17 inhibitor secukinumab was initiated." (PMID 42256376, 2026). "This therapeutic antibody indeed inhibited proliferation of B lymphocytes and TNF production by dendritic cells and is being tested in clinical trials to treat B cell mediated autoimmune diseases." (PMID 42284279, 2026). "TNF-α inhibitors have been shown to reduce systemic inflammation in autoimmune diseases, and their potential role in modulating T-helper cell differentiation in metabolic disorders warrants further investigation." (PMID 41030441, 2025). "Monoclonal antibodies, neutralizing TNFα and IL-1β (anti-TNFα and anti-IL-1β), emerged as a significant treatment option for central nervous system (CNS) autoimmune diseases." (PMID 40338234, 2025). "TNF and CXCL10 are critical cytokines involved in inflammatory responses and immune cell activation, associated with various autoimmune diseases." (PMID 41383128, 2025). "Further research is warranted to better characterize the clinical manifestations and outcomes of cryptococcal infections in patients with autoimmune diseases receiving combined immunosuppressive therapy, particularly corticosteroids and anti-TNF agents." (PMID 41439945, 2025).
autoimmune disease (continued). "Although TNF-α-blockade is an approved treatment for several autoimmune diseases there are cases of paradoxical induction of autoimmunity appearing under anti-TNF therapy, even of diseases that are usually treated with TNF-blockers." (PMID 41142785, 2025). "Well-established role in inflammation; TNF-α inhibitors exist and are widely used in autoimmune diseases." (PMID 40217801, 2025). "TNF-α is a key biological agent for treating autoimmune diseases and a critical factor in maintaining the structure and function of tuberculous granulomas." (PMID 40406513, 2025). "Necroptosis is mainly induced by extracellular factors (TNFα) and participates in pathophysiological processes in various diseases, such as neurodegenerative diseases, cancer, and autoimmune diseases." (PMID 40636901, 2025). "M1 macrophages are an important source of many inflammatory cytokines, including TNF-α, IL-1, IL-12, IL-18, and IL-23, which have been identified as important mediators and drivers of chronic inflammatory and autoimmune diseases." (PMID 39858200, 2025). "These novel approaches aim to provide safer, more effective, and cost-efficient treatments for TNF-mediated inflammatory and autoimmune disorders." (PMID 40807350, 2025). "Although TNFα inhibitors have improved the quality of life of many patients with autoimmune diseases, a significant proportion of patients remain in a progressive disease state and poor quality of life due to the failure of anti-TNFα therapy." (PMID 40469293, 2025). "Several disease markers are often seen in autoimmune diseases, such as IL-6, IL-1β, and tumor necrosis factor-α (TNF-α), with IL-6 being one of the key markers." (PMID 39968418, 2025). "For non-pregnant AOSD patients, IL-1 inhibitors are recommended as first-line biologics agents, while EULAR notes that TNF-α antagonists are the most frequently used in pregnant patients with autoimmune diseases." (PMID 40703281, 2025). "Th1 cells secrete cytokines such as IL-2, IFN-γ, and TNF-α that function in cellular immunity and delayed hypersensitivity inflammatory responses, and play an important role in autoimmune diseases and host resistance to intracellular pathogen infections." (PMID 40804957, 2025). "The effects of ADA were mostly learned from early biologics such as tumor necrosis factor (TNF) inhibitors in the context of autoimmune disease." (PMID 39590882, 2025). "TNF-α inhibitors are used to treat various inflammatory and autoimmune diseases, including HS, but in rare cases, adalimumab has been associated with paradoxical inflammatory adverse events (PAEs), such as posterior uveitis." (PMID 41142785, 2025). "The future of TNF research is aimed at optimizing its therapeutic potential, particularly in autoimmune diseases and cancer treatment." (PMID 41376630, 2025). "TNF blockers have been successfully developed and used in the clinical treatment of autoimmune disorders." (PMID 39093345, 2025). "IL-6 and TNF-α are well known to be involved in pathogenesis of chronic inflammation, autoimmune diseases, and cancer." (PMID 40496000, 2025). "TNF-α is an important mediator in inflammatory processes, autoimmune diseases, and allergic reactions." (PMID 40002575, 2025). "The immunomodulatory effects of Schistosoma infection produce the cytokine IL-10, which can inhibit the production of pro-inflammatory mediators like IFN-γ, TNF-α, and nitric oxide helping in controlling autoimmune diseases." (PMID 40299229, 2025). "For instance, SERPINA1 can affect tumor necrosis factor α (TNF-α) signaling, which is critical in autoimmune diseases." (PMID 40294019, 2025). "In another separate research, multivalent aptamers that target IL-6 and TNF-α were designed to control inflammatory reactions in autoimmune disorders." (PMID 40870970, 2025).
autoimmune disease (continued). "Although adalimumab plays a crucial role in the treatment of autoimmune diseases by specifically inhibiting TNF-α and is significantly improving outcomes for many patients, its use is not without risks." (PMID 41142785, 2025). "TNF is an important pro-inflammatory cytokine, the level of which is increased in many autoimmune diseases; therefore, TNF inhibitors are widely used in the therapy of these nosologies." (PMID 40427602, 2025). "Other biologics such as infliximab and adalimumab, both of which target tumor necrosis factor-alpha, have been used in refractory cases of autoimmune diseases." (PMID 40003315, 2025). "TNFα is a pro-inflammatory cytokine with multiple roles in innate and adaptive immune responses, and biologics that target TNF and TNF receptors are among the most successful drugs for the treatment of chronic inflammatory and autoimmune diseases." (PMID 39996775, 2025). "Adalimumab, marketed as Humira, is a fully humanized monoclonal antibody that blocks the activity of tumor necrosis factor-alpha and is used in treating several autoimmune disorders." (PMID 40525119, 2025). "A major paradox in the field of autoimmunity revolves around the TNFα pathway, presumably relating to the different genetic architectures of human autoimmune diseases 28,29." (PMID 40475455, 2025). "Polymorphisms in genes encoding TNF and its receptors (TNFR1 and TNFR2) are associated with variations in their expression and function, as well as susceptibility to inflammatory and autoimmune diseases." (PMID 40299450, 2025). "Clinically approved TNF-α inhibitors have demonstrated remarkable efficacy in managing various autoimmune diseases." (PMID 40299229, 2025). "In another study, multivalent aptamers that target IL-6 and TNF-α were intended to control inflammatory responses in autoimmune disorders." (PMID 40870970, 2025). "MLN4924 has potential to attenuate IL-17A-induced autoimmune diseases by reducing the secretion of various inflammatory cytokines, including IL-1β, IL-6, TNF-α, and MCP-1." (PMID 40040717, 2025). "Tumor Necrosis Factor alpha inhibitors (TNFi) are widely used in the clinical setting to treat severe autoimmune diseases as they have shown promising efficacy and safety." (PMID 40469293, 2025). "None of the reviewed evidence suggests we are ready to treat migraines with cytokine inhibitors directly (as is done in some autoimmune diseases), but it opens the door to research on, say, IL-6 inhibitors or TNF inhibitors in refractory CM." (PMID 41377228, 2025). "Several in vitro and in vivo studies demonstrated the dysregulation of TNF-α in autoimmune disease patients." (PMID 41346622, 2025). "Recent studies across autoimmune diseases have examined the feasibility and safety of tapering TNF inhibitors in patients with sustained remission." (PMID 41007651, 2025). "Particular attention is given to TNF receptor signaling pathways, the balance between protective and pathological immune responses, and the modulation of TNF activity during anti-TNF therapy in patients with autoimmune diseases." (PMID 40427602, 2025). "TNF-α is a cytokine with diverse functions, primarily responsible for promoting inflammation and contributing to the pathogenesis of autoimmune diseases." (PMID 40573262, 2025). "Tumor necrosis factor alpha (TNF-α) is an important cytokine that frequently contributes to the pathogenicity of autoimmune diseases." (PMID 41346622, 2025). "T cells were also an important source of TNF in allergy and autoimmune disease, in which adaptive immune response plays a major role." (PMID 40185981, 2025). "Adalimumab is a fully human monoclonal antibody against TNF-α, widely used for autoimmune diseases like rheumatoid arthritis, ankylosing spondylitis, and Crohn’s disease." (PMID 41450349, 2025). "The introduction and integration of TNF α inhibitors into clinical practice marked a significant milestone in the therapeutic approach to autoimmune diseases." (PMID 40525119, 2025).
autoimmune disease (continued). "Patients with autoimmune diseases, particularly those with AA, often exhibit elevated serum TNF‐α levels compared with healthy individuals." (PMID 40260013, 2025). "Among them, TNF-alpha is a pro-inflammatory cytokine being involved in the development and progression of several inflammatory and autoimmune diseases." (PMID 41141269, 2025). "Integrating genetic insights into clinical practice can enhance treatment efficacy, minimize adverse reactions, and ultimately improve patient outcomes in the management of autoimmune diseases and other conditions requiring TNF inhibitor therapy." (PMID 41346622, 2025). "MS is an autoimmune disease induced by autoreactive T lymphocytes that is characterized by an imbalance of pro-inflammatory cytokines, such as TNF, interferon γ (IFN-γ), IL-2 and lymphotoxin, and regulatory cytokines (e.g., IL-4 and IL-10)." (PMID 40076462, 2025). "TRAF3 is part of other annotated pathways, such as NOD-like receptor signaling, RIG-I-like receptor signaling, IL-17 signaling, and TNF signaling, all known to be altered in autoimmune diseases and MS development (35, –37)." (PMID 40577117, 2025). "TXNDC5 is overexpressed under hypoxic conditions and autoimmune diseases, functions as a stress survival factor, and is involved in angiogenesis in response to TNF-α and in the inflammatory response through the NF-κB signaling pathway." (PMID 39859202, 2025). "TNF-α plays a pivotal role in the pathogenesis of immune-inflammatory diseases, and TNF-α inhibitors have been widely applied in the clinical treatment of autoimmune diseases." (PMID 40621455, 2025). "Biologic medications, particularly those targeting TNF-α, play a crucial role in suppressing the immune system, reducing inflammation, and preventing joint damage in autoimmune diseases such as RA." (PMID 41158918, 2025). "Diagnosis becomes more complex when overlapping autoimmune diseases such as Crohn’s disease are present, especially in patients receiving immunosuppressive or biologic agents such as anti-tumor necrosis factor-alpha (TNF-α) therapies." (PMID 41450349, 2025). "Tumor necrosis factor (TNF) is a key inflammatory molecule whose up-regulation plays a crucial role in the development and pathogenicity of many autoimmune diseases." (PMID 41346622, 2025). "Although autoimmune diseases exhibit a wide range of pathophysiological mechanisms, common inflammatory markers such as IL-6, TNF-α, and interferon-gamma (IFN-γ) play a role in both autoimmunity and neuroinflammatory processes." (PMID 40002916, 2025). "The development and progression of numerous inflammatory and autoimmune diseases are significantly influenced by TNF-α, a major mediator of inflammation." (PMID 40430212, 2025). "Adalimumab, a monoclonal antibody targeting tumor necrosis factor α, treats autoimmune diseases but induces antidrug antibodies in 30% to 60% of patients, reducing its efficacy." (PMID 41359928, 2025). "Dysregulation of TIM-3 expression has been associated with excessive or inhibited inflammatory responses, leading to autoimmune disease and pregnancy complications, while TNF-α and IL-6 have a well-documented role in TAI pathogenesis." (PMID 39595192, 2024). "Studies have indicated that dysfunctional TNF pathway signaling plays important roles in the occurrence and development of many diseases, such as inflammatory and autoimmune diseases, cancer, and cardiovascular disease." (PMID 37789643, 2024). "Several therapeutic approaches targeting T cell activation (i.e., Janus kinase inhibitors) and proinflammatory cytokines (i.e., antibodies against IL17, IFNγ, and TNFα) have been developed for the treatment of autoimmune disorders." (PMID 38323310, 2024). "Most studies were case reports (n = 44) or case series (n = 11) reporting either cases of IRIS in patients treated for TB who were taking anti-TNFα agents for inflammatory/autoimmune disease or TB-IRIS cases treated with anti-TNFα." (PMID 38957691, 2024).
autoimmune disease (continued). "Our study showed that the inhibitory effects of a TNF-deactivating peptide antagonize inflammation and protect against joint destruction in the autoimmune disease model." (PMID 38839973, 2024). "This explains why healthcare providers undergo extensive screening for M. tb prior to initiating therapy in those individuals with autoimmune diseases who are subjected to anti-TNF-α therapy." (PMID 39066368, 2024). "Firstly, we detected IL-2, IL-4, IL-5, IL-13, IL-17A, IL-17F, IL-22, IFN-γ, and TNF-α in the plasma to exclude the influence of infection or autoimmune disorders, and the standard curves were verified." (PMID 38343544, 2024). "Tumour necrosis factor alpha (TNFα) is recognised as a key function in autoimmune disease, where excessive activation of TNFα mediates cytotoxic and pro-inflammatory responses via TNFR1." (PMID 38368354, 2024). "Given TNF-α’s detrimental role in autoimmune disease, targeting its removal or neutralization is a promising therapeutic strategy." (PMID 39411715, 2024). "These included signaling pathways involved in inflammation such as TNF-alpha and NF-κB signaling, autoimmune disease and infection pathways, and mitogen-activated protein kinase (MAPK) signaling pathways." (PMID 38228657, 2024). "TNF inhibitors have demonstrated significant efficacy in reducing inflammation related to various autoimmune diseases." (PMID 38560169, 2024). "Biologics targeting specific cytokine pathways are widely used in the treatment of autoimmune diseases, including but not limited to Th2 cytokines (IL-4, IL-5, and IL-13), Th17 cytokines (IL-6, IL-17, and IL-23), and TNF-α." (PMID 39403935, 2024). "Many autoimmune diseases are currently being treated with antibodies that inhibit the actions of certain cytokines, such as (IL-6) or tumor necrosis factor (TNF)." (PMID 38255240, 2024). "Transplanted MSC stimulates the secretion of L-amino-acid oxidase (LAAO), a response triggered by elevated levels of tumor necrosis factor-α (TNF-α) in mice with autoimmune diseases through the NF-κB pathway." (PMID 39251573, 2024). "Tumor necrosis factor-α (TNF-α) plays a pivotal role in the pathogenesis of numerous autoimmune diseases, having a significantly higher production than in individuals who do not present with such a disease." (PMID 38398414, 2024). "Observational studies and clinical trials in women with autoimmune diseases receiving TNF inhibitors have reported successful ovulation induction, conception, and healthy deliveries." (PMID 39597081, 2024). "Tumor necrosis factor-alpha (TNF-α) antagonists, a class of biologic agents, have revolutionized the treatment of autoimmune diseases by targeting the inflammatory cascade." (PMID 39639969, 2024). "Pharmacological antagonists of TNF-alpha are currently used for the treatment of autoimmune diseases." (PMID 38731835, 2024). "This TNF inhibitor-induced autoimmune disease spectrum covers a wide range, from mild serologic changes to a full-blown systemic autoimmune disease, causing severe end-organ damage." (PMID 38842591, 2024). "Tumor necrosis factor (TNF) is a crucial cytokine in inflammatory reactions, and drugs that neutralize TNF are successful in treating chronic inflammatory and autoimmune diseases." (PMID 39519210, 2024). "TNF-α inhibitors have demonstrated a strong safety and efficacy profile in 11 autoimmune diseases, with approvals for pediatrics and adult indications." (PMID 39411715, 2024). "Given its role as a TNF-α inhibitor, etanercept potentially holds significant advantages for treating autoimmune disorders." (PMID 39257904, 2024). "This is consistent with previous findings of the beneficial metabolic effect of anti-TNF-α in the treatment of another autoimmune disease in patients who developed additionally T1DM." (PMID 39420138, 2024).